IDH1 (isocitrate dehydrogenase (NADP(+)) 1)
Diseases named in the same sentence as IDH1 in open-access papers (continued):
Sharing a sentence is not in itself a finding about the gene and the disease.
glioma (continued). "Cell experiments for the first time reveal that the IDH1 mutation byproduct, D-2HG, effectively inhibits the ITGB4/PI3K/AKT pathway, thus exerting potent anti-glioma effects and offering insights into its mechanism of action, including its synergistic effect with TMZ." (PMID 38982076, 2024). "Interestingly, the enzyme LDHB, which is involved in converting lactate to pyruvate, and the lactate importer MCT2 are more abundant in IDH1 mutant glioma tissue compared with wildtype samples." (PMID 39596840, 2024). "In vitro internalization studies demonstrated significantly higher uptake of [18F]AG-120 in U251 human high-grade glioma cells with stable overexpression of mutant IDH1 (IDH1R132H) compared to their wild-type IDH1 counterpart (0.4 vs. 0.013% applied dose/μg protein at 120 min)." (PMID 37982850, 2024). "In a cohort of 43 pediatric patients with newly diagnosed WHO grade 3 or 4 gliomas treated on the Children’s Oncology Group ACNS0423 study, IDH1 mutations were detected in 7 of 43 (16.3%) of children with primary malignant gliomas, and no IDH2 mutations were identified." (PMID 39876890, 2024). "Surprisingly, none of the rat gliomas examined in this study harbored mutations in Idh1/2 genes that are common in human gliomas." (PMID 38232086, 2024). "This suggests that IDH1 mutation and TMZ treatment decrease ITGB4 expression in gliomas." (PMID 38982076, 2024). "We conclude that targeting fatty acid metabolism through HDAC inhibition and/or FASN inhibition may be a novel therapeutic opportunity in IDH1 mutant gliomas." (PMID 39149696, 2024). "Furthermore, addition of MR diffusion to conventional MRI features significantly improved the diagnostic value in preoperative prediction of IDH1, MGMT, and ATRX in patients with glioma." (PMID 38486342, 2024). "As a result, quantitative analysis of sub-clonal populations may provide more clarity for the treatment of IDH1 mutant gliomas." (PMID 39596840, 2024). "The level of PE may serve as an indicator for tumor-specific IDH1 status and a potential therapeutic target in the treatment of aberrant metabolic pathways in glioma." (PMID 39021629, 2024). "A genetically modified mouse model with IDH1 R132H mutation and PDGF overexpression was proposed, reflecting the phenotypic features of human gliomas, including 2-HG production, hypermethylation, and differential expression of a number of genes in comparison with a tumor without mutation in IDH1." (PMID 39768176, 2024). "Finally, we found that l-glutamine increased α-KG levels and augmented the differentiation-promoting effects of AGI5198, an IDH1-mutant inhibitor, in IDH1-mutant glioma cells." (PMID 39872214, 2024). "For instance, the reduction of TET2 enzyme levels by promoter methylation in absence of TET2 mutation was reported recently in low-grade diffuse astrocytomas, suggesting that this represents an additional pathomechanism in IDH1- and IDH2-mutated low-grade gliomas." (PMID 39090080, 2024). "This phenomenon suggests that the combination of D-2HG and TMZ might explain why IDH1-mutant patients exhibit enhanced sensitivity to TMZ treatment with the combination showing therapeutic potential in glioma treatment." (PMID 38982076, 2024). "Moreover, immunoblotting results also indicated that the IDH1 mutation increased GLUD1 expression in OGDH-silenced U87 cells, which was consistent with the changes observed in IDH-mutated gliomas." (PMID 39872214, 2024). "In this study, we show that IDH1 MT gliomas are sensitive to VPA treatment." (PMID 39149696, 2024). "The results of the current study show that glioma patients with IDH1-mut had a median OS of 21 months versus 17.5 months for those without an IDH1 mutation." (PMID 38893240, 2024). "Accordingly, these data further support the notion that the agonizable state of innate immune signaling in ATRX-deficient glioma exists largely independent of IDH1 mutational status." (PMID 38272925, 2024).
glioma (continued). "Thus, we delved into and elaborated the lncRNA CRNDE and IDH1 overexpression and miR-23b-3p expression downregulation in human glioma cells (U-118MG, U251 and U87), which is in line with the previous reports." (PMID 37934582, 2023). "For instance, in brain cancers, one can differentiate subtypes of medulloblastoma (T027), 1p/19q codel gliomas (T044), as well as those with/without IDH1 mutations (T030 and T029), and ependymomas (T032), among others." (PMID 36932241, 2023). "Besides, we also found that IDH1 and ATRX mutations, as representative molecular features of gliomas, had a high frequency in each group." (PMID 37488496, 2023). "Additionally, FDA-approved drugs like ivosidenib and enasidenib targeting IDH1 and IDH2, respectively, demonstrated clinical efficacy in IDH-mutated AML, glioma, and cholangiocarcinoma, either alone or in combination." (PMID 38003566, 2023). "Co-mutation between IDH1 and ATRX is well described in gliomas." (PMID 36883553, 2023). "IDH1/2 gene and TERT promoter mutations are more frequent in patients with glioma." (PMID 37250582, 2023). "Similarly, whole‐tumor histograms, as well as texture analysis of FA maps, enabled prediction of the IDH1‐mutation and 1p/19q‐codeletion status in patients with WHO grade II gliomas." (PMID 36866773, 2023). "However, there is no FDA-approved qPCR kit for detecting SNPs in patients with glioma, as the Abbott RealTime IDH1/2 kits are approved for patients with acute myeloid leukemia." (PMID 37908227, 2023). "We show that IDH1 mutational status determines expression of innate-immune molecule long pentraxin 3 (PTX3), which negatively regulates autophagic flux and genes associated with ferritinophagy in gliomas." (PMID 37476290, 2023). "Glioma development did not occur when mutant Idh1 was expressed in a genetic background with loss of Cdkn2a, Atrx, and Pten in vivo." (PMID 36765553, 2023). "Additionally, IDH1-mutant gliomas rely on oxidative phosphorylation, while IDH1-wildtype gliomas primarily rely on glycolysis for ATP production." (PMID 37108511, 2023). "The aim is to use Crispr-Cas12a for the rapid detection of the single nucleotide polymorphism (SNP) of isocitrate dehydrogenase 1 (IDH1)-R132H locus and explore the effectiveness and consistency of this method with direct sequencing method for detecting IDH1-R132H of glioma tissue samples." (PMID 37029174, 2023). "In our study, we examined how the expression of IDH1 mutation and MGMT promoter methylation are linked to the cognitive functioning following the operative treatment in the cohort of all Slovene Grade III and Grade IV glioma patients." (PMID 37341199, 2023). "Univariate analysis showed that tumor WHO grade, resection range, preoperative Karnofsky performance status score, postoperative radiotherapy and chemotherapy, IDH1/2 gene and TERT promoter mutation influenced postoperative survival of patients with glioma (P<0.05)." (PMID 37250582, 2023). "We downloaded nine scRNA-seq datasets of five gliomas from the GEO website, including glioblastoma (GBM), diffuse H3K27M glioma (H3K27M glioma), medulloblastoma (MB), 1p/19q codeleted oligodendroglioma (oligodendrocyte or OD), and IDH1-mutant anaplastic astrocytoma (astrocytoma or IDH1-mutant AA)." (PMID 37693314, 2023).
glioma (continued). "The mean value of the obtained early-passage IDH1 R132H glioma cell cultures’ doubling time was near 60 h, which is close to values obtained for the astrocyte cell line SVGp12 with lentiviral-induced IDH1 R132H mutation that required approximately 60 h to double the cell population." (PMID 36835465, 2023). "Histologically it is characterized as a diffusely infiltrating glioma with mitotic activity, showing no mutations in IDH1, IDH2 or H3-genes." (PMID 37561227, 2023). "Furthermore, flow cytometric analysis of single-cell suspensions from brain tissue of mice with IDH1-mutant gliomas displayed significantly fewer CD45+ immune cells compared with brain tissue of mice with wildtype Idh1 gliomas." (PMID 36765553, 2023). "The previous findings identify HDAC6 as a potential specific target for IDH1 mutant gliomas." (PMID 37528157, 2023). "TET2 mutations are rare in glioma and neither Tet2 nor IDH1 knockout mice spontaneously generate brain tumors." (PMID 37528157, 2023). "They achieved an AUC of 0.84 for IDH1 status prediction in glioma." (PMID 37958364, 2023). "Mouse and human models of IDH1 mutant glioma were validated by measuring 2-HG levels." (PMID 37528157, 2023). "However, GDH2 plays an important role in eliminating the growth-inhibiting effect of IDH1 (R132H) mutant gliomas." (PMID 36959802, 2023). "In glioma cell lines, R-2HG inhibited their proliferation in IDH1/2 wild-type lines." (PMID 37444417, 2023). "In contrast, patients >55 years old who have grade 4 gliomas that test negative for the IDH1 R132H mutation can be assumed also to be wildtype for the less common IDH variants and declared to have IDH-wildtype glioblastoma WHO grade 4." (PMID 38157879, 2023). "In addition, ER-phagy is essential for the proliferation and clonogenicity of mutant IDH1 gliomas due to the downregulation of phospholipid biosynthesis." (PMID 37174088, 2023). "Furthermore, the SMR arm of this study included one IDH-1-mutated high-grade glioma, whereas the GTR arm included only IDH-1 wild-type GBs." (PMID 36980659, 2023). "For example, IDH1 is one of the most common molecular assays for gliomas." (PMID 38111705, 2023). "It was previously reported that 5-Aza sensitized only IDH1-mutant gliomas." (PMID 37894860, 2023). "Since 2016, the WHO Tumor classification has dichotomized gliomas by the presence or absence of an IDH1/2 mutation." (PMID 37345193, 2023). "Finally, we developed an IDH1-related signature for evaluating the prognosis of WHO grade 4 glioma patients with the CGGA dataset." (PMID 37952042, 2023). "Moreover, in vitro and in vivo studies have shown that mutant IDH1 promotes TAM migration: the conditioned medium derived from IDH1 mutant glioma cells significantly increases TAM infiltration compared with IDH1 wild-type glioma cells." (PMID 37296846, 2023). "Interestingly, IDH-wildtype gliomas utilize glutamine and glucose for metabolic pathways, whereas IDH1-mutant gliomas depend on glutamate and lactate." (PMID 37108511, 2023). "Thus, extracellular IDH1 within tumors has broad potential to guide patient selection, predict success, and perhaps enhance clinical efficacy of immunotherapy for gliomas." (PMID 37161052, 2023). "γ-H2AX assay showed that IDH1-mutant glioma cells had higher radiosensitivity than wild-type." (PMID 37952042, 2023). "New IDH1 mutant glioma models are needed to examine the spectrum of responses to treatment, which may be observed clinically following the administration of IDH1 mutant inhibitors." (PMID 37296846, 2023).
glioma (continued). "Conditioned medium experiments further suggested that tissue homogenates from IDH1-mutant mouse gliomas may contain lower levels of neutrophil chemoattractants." (PMID 36765553, 2023). "Studies have found that the IDH1 molecular phenotype is also closely related to glycolytic energy metabolism in glioma cells, and the aerobic glycolytic capacity of IDH1WT GBM cells is significantly higher than that of IDH1R132H GBM cells, which is consistent with results obtained in this study." (PMID 37066523, 2023). "Among the JH MTB cohort of patients with IDH1 wild-type high-grade gliomas who received targeted therapies, trametinib monotherapy or in combination with dabrafenib conferred radiographic partial response in 75% of patients harboring BRAF or NF1 actionable mutations." (PMID 38143440, 2023). "The expression of LOX family genes is influenced by the IDH1 status of gliomas." (PMID 36825022, 2023). "Kaplan-Meier survival curve showed that IDH1/2 gene and TERT promoter mutation were significantly different from those of wild-type patients, again, it is suggested that IDH1/2 gene and TERT promoter mutations are related to the survival of patients with glioma." (PMID 37250582, 2023). "Concerning tumor molecular profiling, the majority of glioma results were IDH1/2 wild-type." (PMID 37238297, 2023). "Of note, patients with grade 4 gliomas with higher predicted risk scores (relative to median) were associated significantly with shorter survival regardless of the IDH1 mutation status (p < 0.05)." (PMID 37580817, 2023). "Thus, neomorphic IDH1-mutant activity leads to a glioma CpG island methylator phenotype (G-CIMP) characterized by concurrent promoter hypermethylation and the silencing of a large number of genes." (PMID 37372972, 2023). "Indeed, IDH1 over-expression in glioma cells prolonged killing by cytolytic T cells (CTL), and extracellular IDH1 enhanced T cell responsiveness to tumor peptide-MHC." (PMID 37161052, 2023). "In general, IDH1-mutant astrocytomas have better prognosis than IDH1/2-wildtype gliomas." (PMID 38012788, 2023). "According to the current WHO classification astrocytomas and oligodendrogliomas are defined as IDH1/2 mutant tumors, with the exemption of circumscribed gliomas that include entities like pilocytic astrocytoma and pleomorphic xanthoastrocytoma as well as pediatric type gliomas." (PMID 36566461, 2023). "In addition to its prognostic significance, IDH1/2mt is also a promising therapeutic target in the treatment of glioma." (PMID 36968138, 2023). "One should be aware that tumors classified in the past as GBM may carry an IDH1/IDH2 mutation or exhibit a G-CIMP phenotype (with or without an IDH1/IDH2 mutation), both of which are prognostic factors for longer survival in glioma patients." (PMID 37999122, 2023). "CCK-8 and EDU assay showed that proliferation capacity of IDH1-mutant glioma cells declined." (PMID 37952042, 2023). "Indeed, additional D‐2HG‐producing IDH1 mutations have been identified in non‐AML tumors, including IDH1 R100 in glioma, IDH1 G97 in colon cancer, and IDH1 Y139 in glioblastoma." (PMID 37601838, 2023). "Another IDH1 inhibitor is FT-2102, used specifically in the treatment of myelodysplastic syndromes and AML, was tested in the adult population with solid tumors and gliomas in which mutation in IDH1 was found." (PMID 37397394, 2023).
glioma (continued). "We demonstrated significantly more favorable neuropathological characteristics, such as IDH1-mutation, lack of anaplasia and lower mitotic rates in incidental diffuse and anaplastic gliomas compared to a group of symptomatic gliomas." (PMID 37043120, 2023). "Scattered tumor cells from the surrounding brain tissues, frequently few in cell numbers, mild in cell morphology, and difficult to identify for low-grade gliomas, could also be detected if they were from an IDH1 R132H-positive tumor." (PMID 36810519, 2023). "IDH1 mutation resulted in significantly shorter survival time in subcutaneous tumor model with CT26 colon cancer tumor, and significantly longer survival time in orthotopic tumor model with GL261 glioma tumor." (PMID 37741882, 2023). "Our study reveals an important additional function for IDH1 mutation in regulating IRF3/7 expression and could help explain the enhanced susceptibility of IDH1mut gliomas to oncolytic viruses." (PMID 37880243, 2023). "Univariate analysis showed that tumor WHO grade, resection range, preoperative KPS score, postoperative radiotherapy and chemotherapy, IDH1/2 gene mutation and TERT promoter mutation significantly affected the postoperative survival of patients with glioma (P<0.05), as shown in Table-II." (PMID 37250582, 2023). "Together, these foundational studies suggested two possible approaches that could be taken to produce a GEMM of IDH1 mutant glioma." (PMID 37051530, 2023). "Besides being associated with global promoter hypermethylation, IDH1 mutation facilitated changes in 3D DNA-conformation by CTCF-anchor methylation and upregulated oncogene expression in glioma, correlating with poor prognosis." (PMID 36411356, 2023). "A stereotactic brain biopsy and subsequent neuropathological evaluations were performed, resulting in a glioma tumor isocitrate dehydrogenase 1 (IDH-1) and 2 (IDH-2) wild type, glial fibrillary acidic protein (GFAP) and oligodendrocyte transcription factor 2 (Olig2) positive." (PMID 37692853, 2023). "Many reports have shown that IDH1/2 mutation can increase the level of lactate, such as lactate levels in mutIDH1 (R132H) in U87 GBM, mutIDH1 (R132H), and mutIDH2 (R172K) in Grade II and III glioma." (PMID 37108242, 2023). "The univariate results showed that tumor grade, surgical resection range, preoperative KPS score, postoperative radiotherapy and chemotherapy, IDH1/2 gene and TERT promoter mutation were the influencing factors of postoperative survival of patients with glioma." (PMID 37250582, 2023). "Overall, the study constructed a prognostic model in glioma, and predicted a lncRNA CRNDE/miR-23b-3p/IDH1 axis, which could potentially be useful for gene therapy of glioma." (PMID 37934582, 2023). "Moreover, mutations of IDH1 and IDH2 have been detected in many types of cancer, including gliomas and myeloid malignant tumors; furthermore, these enzymes have been confirmed to be closely related to the occurrence and development of cancer." (PMID 38139250, 2023). "Also, variations in spectral bandscorresponding to protein were seen between IDH1 wild type and IDH1mutant gliomas." (PMID 37576695, 2023). "This suggests that targeting GDH2 could be a beneficial strategy for treating patients with IDH1 mutant gliomas." (PMID 36959802, 2023). "Interestingly, triptolide, the second most selective compound, was independently verified by another group as effective against IDH1 mutant glioma cells." (PMID 37528157, 2023). "IDH1/2 gene and TERT promoter mutations are more frequent in patients with human glioma." (PMID 37250582, 2023). "Furthermore, glioma samples harbouring mutant IDH1 accumulate significantly lower 5hmc and significantly higher 5 mc than those containing wild-type IDH1, in accordance with reduced TET activity." (PMID 35389425, 2023).